IRF7 (interferon regulatory factor 7)
Diseases named in the same sentence as IRF7 in open-access papers (continued):
Sharing a sentence is not in itself a finding about the gene and the disease.
breast cancer (continued). "Lastly, an analysis of matched primary breast cancer tumors and bone metastases revealed that primary tumor cells expressed IRF7, whereas metastases consistently demonstrated downregulation of IRF7 expression." (PMID 33408718, 2020). "The silencing of IRF7 in breast cancer cells promoted bone metastasis through tumor immune escape, while the IRF7-driven suppression of metastasis was reliant on IFN signaling to host immune cells." (PMID 32308549, 2020). "Analysis of publicly available murine breast cancer bone metastasis datasets revealed that interferon regulatory factor Irf7, whose expression is repressed during bone metastasis (GSE37975), is upregulated by the SAM + 25(OH)D combination treatment." (PMID 32714613, 2020). "Downregulation of IRF7 has been described in breast cancer and contributes to tumor metastasis, indicating that IFN signaling is involved in the control of metastatic spread." (PMID 31805977, 2019). "High IRF7 pathway activity in primary breast cancer predicted bone relapse-free survival in patients and protected against bone metastasis in mice, and treatment with IFN-α improved bone metastasis-free survival." (PMID 30546090, 2019). "In this work, we demonstrate that sustained activation of the IFN-β/IFNAR/IRF7 signaling axis in chemotherapy-treated ER− breast cancer cells instigates immunological dormancy." (PMID 30546090, 2019). "Suppression of IRF7-regulated genes was shown to be crucial for the induction of bone metastasis in breast cancer, while restoration of IRF7 in tumor cells or administration of IFN, reduced metastasis in mice in a NK and CD8+ T-cell dependent manner." (PMID 30186768, 2018). "Unfortunately, the immune surveillance of breast cancers has been found to be compromised as the IRF7 pathway inside of breast cancer cells is suppressed." (PMID 30011807, 2018). "In a syngeneic mouse model of mammary tumor metastasis using 4T1.2 cells, Bidwell and coworkers identified a number of IRF7 target genes that are suppressed in bone metastases." (PMID 28408907, 2017). "Down-regulation of interferon regulatory factor 7 (Irf7) in breast cancer cells further decreases MHC molecule expression on tumor cells further enhancing immune escape and promoting bone metastasis." (PMID 29037250, 2017). "Real-time PCR and Western blot analyses were used to assess mRNA and protein levels of IFITM1, PLSCR1, STAT1, STAT2, and IRF-7 in AI-resistant MCF-7:5C breast cancer cells and AI-sensitive MCF-7 and T47D cells." (PMID 25588716, 2015). "Finally, knockdown of IRF7 in breast cancer cells significantly diminished the ability of Teniposide to induce NMI following Teniposide treatment." (PMID 38719798, 2024). "Indeed, IRF7 is involved in the active immune surveillance against dormant breast cancer cells (DBCCs) and, when restrained, metastatic outgrowth can appear." (PMID 36902406, 2023). "IRF7 that is regulated by miR-762 could inhibit the proliferation and invasion of breast cancer cells." (PMID 37251373, 2023). "Interferon regulating factor 7 (IRF7) was shown to have a distinct role in bone metastasis since its elevated expression in primitive cancer cells correlated with bone metastasis-free survival in breast cancer patients." (PMID 36902406, 2023). "The regulation of IRF7 mRNA confirms a previous study in with poly(I:C) in breast cancer cells." (PMID 35737804, 2022). "When MT was expressed in human breast cancer cells we found that the interferon response depended on the presence of RNaseL and interferon regulatory factor 7 (IRF7), the key effector molecules at the proximal and distal ends of the OAS-RNaseL signaling pathway." (PMID 35505346, 2022). "However, according to the literature, IRF7 is significantly correlated with breast cancer development." (PMID 32616754, 2020). "In addition, miR-762 was shown to increase breast cancer cell proliferation and invasion by targeting IRF7 expression." (PMID 31235686, 2019).
breast cancer (continued). "Similarly, we find that high expression of IRF7 is correlated (P = 0.029) with positive breast cancer patient outcome in Luminal A subtype." (PMID 28957321, 2017). "Silencing of IRF7 pathways in breast cancer accelerated bone metastasis through immune escape." (PMID 25108500, 2014). "Our finding for IRF7 is consistent with a recent study that used a mouse model of breast cancer metastasis to show that bone metastases were suppressed in the presence of IRF7 expression, and that this phenomenon depended on interferon signaling and functional immune cells." (PMID 24994117, 2014). "However, miR-762 downregulates IRF7, enhancing breast cancer proliferation and invasion." (PMID 41262249, 2025). "A nomogram was constructed using 7 IRGs, including GPR132, IFITM1, IL12B, IL18, IRF7, KCNMB2, and TACR1, to predict the 1-, 2-, and 3-year survival of breast cancer patients." (PMID 37304237, 2023). "In breast cancer cells, IRF3 and MyD88 mRNAs were detected while IRF1 and IRF7 mRNAs were upregulated." (PMID 35737804, 2022). "To assess this, we used a panel of human breast cancer cell lines and as with our observed expression in primary tumor tissues, the expression of IRF9 and IRF7 was heterogeneous across cell lines and subtypes." (PMID 31482136, 2019). "To test whether chemotherapy treatment was able to directly induce IRF7 expression in different cell lines, we treated murine (4T1 and D2A1) and human (MDA-MB-231 and MDA-MB-468) breast cancer cell lines for 24 h with high doses (IC85) of MTX and DOX." (PMID 30546090, 2019). "For example, in preclinical models of spontaneous mammary tumour metastasis to bone, restoration of interferon regulatory factor 7 (IRF7) expression in the tumour cells did not alter primary tumour growth but did inhibit bone metastasis." (PMID 30514977, 2019). "Indeed, there were 5 genes that were present in our list and in the up regulated list for breast cancer (RAP2C, SPN, GINS2, ESPL1 and IRF7)." (PMID 29108258, 2017). "Interestingly, the gene sets of ISs (AIM2, IFIH1 and TLR3), ISs and IFN-β (IFNB1), and all (ISs, IFNB1, IRF7 and TRAIL) showed strong correlations in ER-negative and lymph node positive or basal-like breast cancer patient survival." (PMID 27077807, 2016). "Next, the expression of NF-κB and IRF7 target genes was investigated by RT-PCR and Western blot in MDA-MB-435-Hyg human breast cancer cells, M13SV1-EGFP-Neo human breast epithelial cells and M13MDA435-1 and -3 hybrid cells that were stimulated with LPS and CpG-ODN for 2, 6, 12, 24 and 48 h." (PMID 27187369, 2016). "Enforcing irf7 expression by tumor cells could restore type I IFN signaling, leading to inhibition of metastatic dissemination in the 4T1.2 breast cancer bone metastasis model." (PMID 23269924, 2012). "IRF3 was not regulated, while IRF7 was upregulated in mammary carcinoma cells (p < 0.05)." (PMID 35737804, 2022). "microRNAs that target IRF7 on the other hand have been linked to its role in regulating oncogenesis and apoptosis rather than IFN induction per se—for example in breast cancer cells, miR-762 targets IRF7, inhibiting proliferation and invasion in a matrigel assay." (PMID 30984161, 2019). "While in M13SV1-EGFP-Neo cells and M13MDA435-3 hybrid cells both CpG-ODN and LPS stimulation resulted in IRF7 activation, no nuclear translocation of this transcription factor was detected in MDA-MB-435-Hyg breast cancer cells and M13MDA435-1 hybrid cells." (PMID 27187369, 2016).
lupus (37 papers, 2007 to 2025). "Lupus-associated single-nucleotide polymorphisms in IRF7, IRF5, and STAT4 are related to elevated levels of IFN-α, and some SLE risk haplotypes of IRF5 have been shown to be associated with increased IFN-α expression in SLE." (PMID 29052537, 2017). "TNF is already targeted by biologic therapeutic approaches, and IFN regulatory factors 3 and 7 (IRF3 and IRF7) have been implicated in the IFN signature in lupus previously." (PMID 27846842, 2016). "IRF7 itself has been identified as a risk factor for human systemic lupus erythematosus and has been shown to be co-regulated along with IRF8 in MS." (PMID 22196084, 2011). "Moreover, interferon regulatory factor 7 (IRF-7) signaling, which has been linked to lupus progression, was also reported inhibited by retinoic acid." (PMID 35677055, 2022). "In addition, the downstream signaling components of TLR7, IFN regulatory factor 5 (IRF5) and IRF7, are closely associated with lupus pathogenesis." (PMID 22952664, 2012). "In addition, proteins that negatively regulate TLR-induced activation of transcription factors IRF7 and NF-κB such as A20, have also been shown to contribute to lupus susceptibility in a combination of either GWAS or candidate gene approaches." (PMID 23227085, 2012). "Recent studies have indicated that polymorphisms in IRF7 gene are associated with immunity-mediated diseases, systemic lupus erythematosus (SLE) and systemic sclerosis." (PMID 30774658, 2019). "Numerous studies have demonstrated that the expression and activation of IRF family members, including IRF3, IRF5, and IRF7, are significantly increased in systemic autoimmune diseases such as systemic lupus erythematosus (SLE) and Sjögren’s syndrome (SS)." (PMID 41383611, 2025). "Meanwhile, the expression levels of IFN-I signature genes (ISGs), such as Mx1, Irf7, Oas1, and Isg15, were increased in the renal tissues of KI lupus mice compared with WT lupus mice." (PMID 35788118, 2022). "In a silica-induced lupus model, DHA inhibited the expression of IRF7 and other IFN-associated genes involved in the inflammatory response." (PMID 36357780, 2022). "Differentially methylated genes between African American and European American lupus patients include type I IFN–response genes such as IRF7 and IFI44, and genes related to the NF-κB pathway." (PMID 33108347, 2020). "These abnormalities are probably related to the dysregulation of IRF7 and CSK genes which are the key lupus susceptibility genes." (PMID 31370803, 2019). "BKs suppressed important ISGs that we have previously shown to be induced upon TLR7 and -9 stimulation in lupus dendritic cells (DCs), especially the IRF7, a key regulator of Type I IFN responses." (PMID 29456540, 2018). "BKs significantly decreased the ISGs induced by TLRs in vitro and in vivo (in normal and lupus-prone mice), and in human PBMCs, especially the induction of Irf7 gene (p < 0.05), the master regulator of Type I IFNs." (PMID 29456540, 2018). "This study aimed to explore the role of apoptosis initiators, caspase-9, caspase-10, mitochondrial anti-viral signaling protein (MAVS), and interferon regulatory factor 7 (pIRF7), in patients with systemic lupus erythematosus (SLE)." (PMID 25370148, 2014). "Further, the type of viral latency cells with high TLR7, IRF-5, and IRF7 (type III) are probably present in lupus patients in vivo." (PMID 22952664, 2012). "Moreover, IPA identified other upstream activators likely critical in the cSiO2-triggered Type 1 IFN (IFNAR, IRF-7, and IFNα) and Type 2 IFN (IFNγ) responses observed here and known to be associated with human lupus." (PMID 38361937, 2024). "TLR-stimulated macrophages from ITGAM SNP carriers with systemic lupus erythematosus showed increased basal expression of IRF7 and IFN-β, whereas activation of CD11b inhibited the LPS-induced pro-inflammatory response in macrophages of mice with endotoxic shock." (PMID 36591261, 2022).
lupus (continued). "Thus, it is likely that in the presence of high levels of IFNα, as seen in some lupus patients and many mouse models of lupus, Irf7 is upregulated and MDSCs downregulated." (PMID 34220829, 2021). "Lupus-associated single-nucleotide polymorphisms are found in genes encoding molecules that participate in the production of IFN-α, such as Toll-like receptor (TLR) 7, IFN-regulatory factor (IRF) 5, and IRF7." (PMID 29052537, 2017). "This novel role for Ro52, in negatively regulating IRF7 stability, may provide a mechanism to protect the host from the overproduction of type I IFNs, a contributing factor to the pathogenesis of systemic lupus erythematosus." (PMID 20668674, 2010). "IRF7 was recently reported to be the master regulator of IFN type I-dependent immune responses, and recent publications have shown that an IRF5 polymorphism is strongly associated with systemic lupus erythematosus (SLE)." (PMID 17490473, 2007). "SLE patients treated with autologous stem cell transplantation show that high expression of IRF7 is correlated with recurrent lupus disease activity." (PMID 37638030, 2023). "Type 1 IFNs increase the cytotoxic function of T cells by upregulating IFN regulatory factor 7 (IRF7) expression, which is responsible for GzmB production in AID, such as autoimmune kidney disease in mice and systemic lupus erythematosus (SLE) in humans and associated glomerulonephritis." (PMID 41009359, 2025). "The CXCR4 agonist clobenpropit robustly suppresses IRF7 phosphorylation, lowers IFN production, and reduces inflammatory cytokines in a lupus model." (PMID 41301504, 2025). "In this study, we employed Mendelian randomization to investigate the potential causal relationship between five genes, namely, DDX58, IFIH1, IRF7, STAT1, and ISG15, and systemic lupus erythematosus (SLE)." (PMID 39445158, 2024). "Another study showed that lupus’ keratinocytes exhibit a heightened response to interferon (IFN), emphasizing the crucial role of IRF7 in the progression of cutaneous lupus erythematosus." (PMID 38022551, 2023). "Irf7 is induced downstream of both Toll-like receptor 7 (TLR7), TLR9, and type I interferon receptor ligation, all key molecules in mouse lupus pathogenesis." (PMID 34220829, 2021). "The minor cluster #11 expressed AXL, IRF4, IRF7, and CD5 genes previously found in AS-DC, Pre-DC, or pDC45,46, but was absent from blood samples; #11 better aligned to transitional DC47 and were mostly observed in HNSCC and in Lupus." (PMID 35418195, 2022). "In SLE and lupus nephritis (LN), IRF3 and IRF7 serve as central drivers of inflammation." (PMID 41383611, 2025).
autoimmune disease (24 papers, 2010 to 2025). A disorder resulting from loss of function or tissue destruction of an organ or multiple organs, arising from humoral or cellular immune responses of the individual to their own tissue constituents. "IRF3 and IRF7 are implicated in various diseases, including cancer, autoimmune disorders, inflammatory diseases, cardiac hypertrophy, psoriasis, bacterial infections, and atherosclerosis." (PMID 39844998, 2025). "IRF7 plays an important role in the pathogenesis of autoimmune diseases such as SLE, and its upregulation is closely associated with disease susceptibility and activity." (PMID 41383611, 2025). "As the master regulator of IFN-I/III, IRF7 has a dual role as a protector and cause of autoimmune diseases." (PMID 37638030, 2023). "Genetic studies have also implicated EBI2 as a regulator of an interferon regulatory factor 7 (IRF7)-driven inflammatory network (IDIN) associated with autoimmune diseases, although the corollary in primary type I IFN-producing cells has not been reported." (PMID 24386204, 2013). "On the other hand, due to its tissue- and cell-specific and important role in autoimmune diseases, the relationship between IFN-I antagonists and IRF7, as well as the regulation of IRF7, is crucial for understanding the development of autoimmune diseases." (PMID 37638030, 2023). "IRF3 and IRF7, which are associated with MyD88-independent pathway of TLR4 signalling, also play crucial roles in development of autoimmune disease or CRSwNP, and these molecules are thought to act as pro-inflammatory transcription factors in these diseases." (PMID 35256715, 2022). "More investigations have focused on SLC15A4 regulating TLR-triggered IRF7-IFN-I axis in autoimmune diseases." (PMID 34168674, 2021). "IRF7 is an important regulator of type I IFN expression, and aberrant production of type I IFN is often associated with autoimmune disorders such as SLE." (PMID 28367002, 2017). "Several modulatory factors in the TLR signaling pathway including IRF3, IRF7, IRF8, TRIM20, MYD88 and NF-κB1 have been associated with autoimmune disease." (PMID 26794091, 2016). "Single nucleotide polymorphisms in the genes for IRF5, IRF7 and IRF8 have also been associated with an increased risk for SLE and other autoimmune diseases." (PMID 23826184, 2013). "Due to its regulatory action on type I IFN signaling, IRF7 therefore represents an important factor that regulates development of CNS autoimmune diseases, such as MS." (PMID 22196084, 2011). "Our findings point to IRF7 as a key signaling intermediate in type I IFN modulation of autoimmune disease." (PMID 22196084, 2011). "Investigating the interaction mechanism between the ubiquitination of the cGAS-STING pathway and the IRF3/IRF7 pathway may elucidate its significant involvement in autoimmune disorders and antiviral responses." (PMID 40028324, 2025). "In addition, more attention should be paid to other loci of IRF7 and the potential roles of IRF7 in other autoimmune diseases." (PMID 30774658, 2019). "Thus, increased IRF7 expression promotes IFN responses in activated immune cells, and increases the susceptibility to autoimmune diseases." (PMID 31370803, 2019). "IRF3, IRF5, and IRF7 were essential for the production of type I interferons (IFNs) upon pathogen recognition by receptors, impacting viral and bacterial infections, inflammatory responses and autoimmune diseases, cancer growth, and metastasis, and changes in the tumor microenvironment." (PMID 38999981, 2024). "Notably, IRF7-mediated pathway of type I IFN responses is mainly initiated by ssRNA sensor TLR7, and previous studies reported that the over-expression or activation of TLR7 is associated with autoimmune diseases." (PMID 31603949, 2019). "Persistent activation of IFN-I signaling represents a key pathological basis of multiple autoimmune diseases, primarily driven by aberrant activation of IRFs, particularly IRF3, IRF5, and IRF7." (PMID 41383611, 2025).